LINC00507 (long independently transcribed non-coding RNA 507)
Gene: Long non-coding RNA gene on chromosome 12 (127,914,707 to 127,960,028, forward strand). Ensembl gene ENSG00000256193.
Diseases named in the same sentence as LINC00507 in open-access papers:
LINC00507 is named in the same sentence as 2 diseases in open-access papers, as found by Europe PMC text mining. Sharing a sentence is not in itself a finding about the gene and the disease. The quoted sentences say what the papers report.
glioma (1 paper, 2023). A benign or malignant brain and spinal cord tumor that arises from glial cells (astrocytes, oligodendrocytes, ependymal cells). "The expression levels of AC062021.1, SNHG6, LINC00507, FAM66C, DGCR10, and LINC00641 were significantly lower in glioma tissues than in normal brain tissues (P < .05) and gradually increased with the degree of malignancy." (PMID 37145002, 2023).
LINC00507 also shares sentences with these, for which no sentence is quoted: Alzheimer disease (1 paper).